BCL10 (BCL10 immune signaling adaptor)
Diseases named in the same sentence as BCL10 in open-access papers (continued):
Sharing a sentence is not in itself a finding about the gene and the disease.
Arthritis (1 paper, 2016). Inflammation of a joint. "The Bcl10−/− mutation also caused partial protection from the clinical signs (P=0.065; two-way ANOVA) and ankle-thickening response (P=0.015; two-way ANOVA) during K/B × N serum-transfer arthritis." (PMID 27032818, 2016). "Therefore, we tested neutrophil functions and arthritis development in the absence of Bcl10." (PMID 27032818, 2016).
chronic hepatitis (1 paper, 2018). An active inflammatory process affecting the liver for more than six months. "MAP2K7 and MAPK14 were highly expressed in chronic hepatitis; LAT, SOS2, and BCL‐10 were highly expressed in normal tissues; PTPN6, LCK, and CTLA4 were highly expressed in CS." (PMID 30259695, 2018).
cyst (1 paper, 2025). A sac-like closed membranous structure that may be empty or contain fluid or amorphous material. "Immunohistochemical staining demonstrated that the neoplastic cells showed diffuse positivity for the acinar markers trypsin and BCL-10, including some areas of cyst lining, thereby confirming acinar differentiation." (PMID 41120769, 2025). "CK19 was positive in cyst lining areas where trypsin/BCL-10 were negative, supporting ductal differentiation in those regions." (PMID 41120769, 2025).
deficiencies (1 paper, 2025). "Mice deficient in BCL‐10 exhibit immune deficiencies due to impaired NF‐κB activation, which consequently hampers immune cell activation." (PMID 40779122, 2025).
dementia (1 paper, 2019). Loss of intellectual abilities interfering with an individual's social and occupational functions. "DS dementia strongly correlates with overexpression of miR-155 on chromosome 21 with concomitant reduction of multiple CNS-functional targets, including BACH1, CoREST1, Cyclin D1, BCL6, BCL10, BIM, and SAPK4." (PMID 31824553, 2019). "Recent evidence suggests that DS dementia strongly correlates with overexpression of miR-155 on chromosome 21 with concomitant reduction of multiple CNS-functional targets, including BACH1, CoREST1, Cyclin D1, BCL6, BCL10, BIM, and SAPK4." (PMID 31824553, 2019).
diabetes (1 paper, 2013). "Since the TLR4 signaling pathway is activated in diabetes and by carrageenan, we addressed systemic and intestinal inflammatory responses following carrageenan exposure in Bcl10 wild type, heterozygous, and null mice." (PMID 23766559, 2013).
eczema (1 paper, 2006). "The most significant SNP was in the gene B cell lymphoma 10 (BCL10) and showed association with facial eczema resistance in a Jersey population." (PMID 17125523, 2006).
enteropathy (1 paper, 2018). "A similar phenotype of enteropathy and Treg deficiency has been observed with BCL10 deficiency." (PMID 29686669, 2018).
gastric cancer (1 paper, 2024). A primary or metastatic malignant neoplasm involving the stomach. "For example, BCL10 has been implicated in the activation of AKT signaling, which supports cancer cell survival and migration, particularly in liver and gastric cancers." (PMID 39469643, 2024).
gastroenteritis (1 paper, 2021). An inflammatory disorder that affects the upper and lower gastrointestinal tract. "At odds with the first case of BCL10 deficiency, the second patient was not reported to have significant gastroenteritis and showed a normal gastroesophageal reflux scan." (PMID 34868072, 2021).
histiocytic neoplasm (1 paper, 2018). Histiocytic tumors are a heterogeneous group of tumors and tumorlike masses commonly associated with histologically identical extracranial lesions.
Hyperglycemia (1 paper, 2017). An increased concentration of glucose in the blood. "Given that hyperglycemia induces chronic inflammation as a causative factor of cardiac remodeling, the expression levels of inflammatory markers, including p-P38, p38, TNF-α, IL-1β, CARD9, and BCL10, were examined by Western blot." (PMID 28272348, 2017).
Hypertension (1 paper, 2025). The presence of chronic increased pressure in the systemic arterial system. "Moreover, deletion of CARD9 and BCL10 decreased hypertension-induced cardiac fibrosis and electrical remodeling, and reduced NF-κB activity 34,35." (PMID 39897024, 2025).
leprosy (1 paper, 2021). Leprosy is a chronic infectious disease affecting primarily the skin and peripheral nervous system. "The BCL10 gene-wise association with leprosy lost significance when conditioning for the p.G213E variant (PSKAT-O = 0.08)." (PMID 34879060, 2021). "SNPs in vicinity of the BCL10 gene were associated with leprosy per se in a large sample of Chinese leprosy patients." (PMID 34879060, 2021). "A significant depletion of protein-altering variants was detected for the IL18R1 and BCL10 genes in leprosy cases." (PMID 34879060, 2021). "Using this approach, we observed a significant depletion of protein-altering variants in leprosy cases for the IL18R1 and BCL10 genes, identifying them as candidate genes for a protective role in leprosy pathogenesis." (PMID 34879060, 2021). "The gene-wise association of BCL10 with leprosy was mainly driven by the common p.G213E variant." (PMID 34879060, 2021). "We found that the burden of amino acid changes in IL18R1 and BCL10 was significantly different between leprosy cases and healthy controls, suggesting these genes as functional candidates in leprosy pathogenesis." (PMID 34879060, 2021). "We identified mutations in four genes (IL18R1, BCL10, CDSN, and PSORS1C2) as candidates for functional mediators of leprosy susceptibility." (PMID 34879060, 2021). "Here, the identification of the BCL10 p.G213E variant being significantly depleted in leprosy cases provided independent support for the role of BCL10 in leprosy pathogenesis." (PMID 34879060, 2021). "When testing the remaining 24 genes for enrichment or depletion of protein-altering variants in leprosy patients compared to healthy controls, the IL18R1 and the BCL10 genes displayed significant evidence for association with leprosy surpassing the multiple testing correction cut-off of P < 0.002." (PMID 34879060, 2021).
malignant brain tumor (1 paper, 2018). "Many RNFs, like RNF8 and RNF168, have an important role in the DDR and are tightly modulated by other RNFs (e.g., RNF169) and scaffold proteins, e.g., histone H1, B-cell lymphoma/leukemia 10 (BCL10), and lethal malignant brain tumor-like 2 (L3MBTL2))." (PMID 30529286, 2018).
marginal zone lymphoma (1 paper, 2023). A usually indolent mature B-cell lymphoma, arising from the marginal zone of lymphoid tissues. "The mutation pattern of the BN2/C1/NOTCH2 group, including mutation of NOTCH2, TNFAIP3, and BCL10 resembles that of marginal zone lymphomas (MZL) 52,53." (PMID 36788062, 2023).
metastatic tumors (1 paper, 2025). "BCL10 was highly expressed in metastatic tumors and significantly inhibited the proliferation of CD8+T cells." (PMID 40539049, 2025).
neuroendocrine neoplasm (1 paper, 2021). Endocrine tumors, also referred to as neuroendocrine tumors (NETs), are defined by a common phenotype which is characterized by the expression of general markers (neuron specific enolase, chromogranin, synaptophysin) and hormone secretion products. "The immunostaining study with the most surface layer of the lesion indicating a neuroendocrine neoplasm revealed partial positive BCL-10 staining." (PMID 33531019, 2021).
non-small cell lung carcinoma (1 paper, 2012). A group of at least three distinct histological types of lung cancer, including non-small cell squamous cell carcinoma, adenocarcinoma, and large cell carcinoma. "To further examine whether CARMA3 and Bcl10 contribute to the invasive capabilities of non-small cell lung cancer cells, we conducted matrigel invasion assays." (PMID 22615840, 2012).
pancreatic ductal adenocarcinoma (1 paper, 2021). An infiltrating adenocarcinoma that arises from the epithelial cells of the pancreas. "In this study, we assessed whether nuclear BCL10 translocation is clinically significant in advanced and metastatic pancreatic ductal adenocarcinoma (PDAC)." (PMID 34412631, 2021).
renal cell carcinoma (1 paper, 2018). "This study showed that CARD9 induced a multiprotein complex with BCL10 proteins, which recruited TRAFs in pVHL-deficient renal cell carcinomas (RCC)." (PMID 29352133, 2018).
renal fibrosis (1 paper, 2025). A final common manifestation of a wide variety of chronic kidney diseases characterized by glomerulosclerosis and tubulointerstitial fibrosis. "In a renal fibrosis model driven by Ang II, Bcl10-deficient mice showed significantly less kidney fibrosis and inflammatory cell infiltration than wild-type, indicating that Bcl10 normally promotes NF-κB–mediated inflammation and fibrogenesis." (PMID 40149956, 2025).
respiratory infections (1 paper, 2021). "All reported BCL10-deficient patients had a sibling who died in the first months of life due to respiratory infections." (PMID 34868072, 2021). "From the diagnostic standpoint, a clinical history of respiratory infections since the first months of age should raise suspicion for BCL10 deficiency, since this clinical manifestation was present in all three patients reported to date." (PMID 34868072, 2021).
testicular cancer (1 paper, 2020). A primary or metastatic malignant neoplasm that affects the testis.
testicular germ cell tumours (1 paper, 1999). "Aberrations within Bcl10, a gene involved in execution of apoptosis, has most recently been found in a variety of cancers, including cell lines of testicular germ cell tumours of adolescents and adults (TGCTs)." (PMID 10408400, 1999).
Zinc deficiency (1 paper, 2017). A deficiency of the essential metal Zinc; an essential cofactor for many enzymes. "HFD and zinc deficiency synergistically induce ORCH by increasing oxidative stress‐mediated activation of BCL10/CARD9/p38 MAPK signalling." (PMID 28158919, 2017). "In the present study, zinc deficiency exacerbated BCL10 and CARD9 expression in obese mice, while zinc supplement reduced the BCL10 and CARD9 levels." (PMID 28158919, 2017). "Administration of SB203580 to HFD mice or specific siRNA in palmitate‐treated cardiomyocytes eliminated the HFD and zinc deficiency activation of p38 MAPK, but did not significantly impact the expression of BCL10 and CARD9." (PMID 28158919, 2017).
tumor (43 papers, 1999 to 2025). "The R58G mutation of BCL10 was first described in a germ cell line tumor and shown to hyperactivate NF-κB." (PMID 35727133, 2022). "Subsequently, we examined the association between nuclear BCL10 expression patterns in tumor cells and the clinical outcomes of patients with recurrent, advanced, and metastatic PDAC who received systemic chemotherapy." (PMID 34412631, 2021). "BCL10 is closely associated with immunosuppression across various tumor types." (PMID 40539049, 2025). "In BJAB B cells stable BCL10-CARD11 expression activates MALT1 and NF-κB as strong as oncogenic variants of CARD11 derived from DLBCL tumor patients, clearly showing that the proximity of BCL10 and CARD11 alone is sufficient to activate downstream signaling pathways." (PMID 30515170, 2018). "Indeed, the cIAP inhibitor Birinapant, which prevents K63-linked ubiquitination of BCL10 impedes tumor growth in ABC DLBCL xenograft models." (PMID 30474008, 2018). "The enriched NF-κB and MAPK pathways, along with its association with T and B cells, suggest that BCL10 may exert its effects by inducing an inflammatory response enhancing killing and inhibiting tumor cell proliferation, further emphasizing its potential significance." (PMID 38289597, 2024). "In this study, through multi-layered bioinformatics analysis and experimental verification, the role of BCL10 on immune cells in the tumor immune microenvironment was systematically investigated." (PMID 40539049, 2025). "In this study, comprehensive bioinformatics and experimental analyses were performed to elucidate the role of BCL10 in shaping the tumor immune microenvironment (TIME)." (PMID 40539049, 2025). "The bioinformatics analysis and in vivo verification revealed an immunosuppressive axis orchestrated by BCL10 in tumor immune microenvironment." (PMID 40539049, 2025). "The expression levels of BCL10 in normal and tumor tissues were compared from the TCGA and GTE databases." (PMID 40539049, 2025). "In cancer, BCL10 dysregulation leads to enhanced tumor growth and immune evasion by promoting pro-survival signals." (PMID 39469643, 2024). "The deleted regions contained the tumour suppressors CDKN2C, SDHB, and SFPQ in 1p and CDKN2A in 9p in metastatic samples and the tumour suppressors BCL10 and NOTCH2 and the oncogenes JAK1 and NRAS in 1p in the non‐metastatic sample group." (PMID 37622176, 2023). "We confirmed previously reported alterations in several components of the NF-κB signaling, including TNFAIP3A (26%), MYD88 (12%), and BCL10 (7%), which were observed in 52 tumor specimens." (PMID 35528192, 2021). "Comparison between the pairs of primary and recurrent tumor samples revealed that 5 genes were concordantly upregulated with a > twofold difference in expression level, including BCL10, BIRC3, CD40, TNFRSF10A and TRAF4." (PMID 34488754, 2021). "We assessed the expression patterns of BCL10 and NF-κB in tumor cells in 136 patients with recurrent, advanced, and metastatic PDAC using immunohistochemical staining." (PMID 34412631, 2021). "In a PANC-1-xenograft mouse model, inhibition of BCL10 expression also attenuated the tumor growth of PDAC." (PMID 34412631, 2021). "Nuclear BCL10 translocation activates NF-κB signaling and contributes to tumor progression and poor prognosis of advanced/metastatic PDAC." (PMID 34412631, 2021). "Taken together, our data suggest that DRI-BPIs represent an effective and safe approach to inhibit BCL10-dependent DLBCL tumor growth in vivo." (PMID 33052237, 2020). "In terms of pathological diagnosis, the immunophenotype analysis showed that the stromal lymphocytes were positive for CD20, CD79a, and BCL-2, while the tumor cells were positive for BCL-10, NF-kB, p65 and PAX-5." (PMID 33585230, 2020). "Consistently, the acute deletion of BCL10 only in Tregs can release protective anti-tumor immune responses." (PMID 31138793, 2019).
tumor (continued). "This panel reflects, in part, tumours reported to have involvement of the 1p22 region of chromosome 1, the region harbouring the Bcl10 gene." (PMID 10408401, 1999). "The results further confirmed that the infiltration level of CD8+T cells in the CESC immune microenvironment was negatively correlated with BC10 expression, and high expression of BCL10 inhibited the infiltration of CD8+T cells in tumor microenvironment (p=0.04, R=-0.12)." (PMID 40539049, 2025). "These computational findings collectively indicate that BCL10 may orchestrate an immunosuppressive TIME by dual mechanisms: suppressing anti-tumor immunity via cytotoxic cell inhibition and amplifying immune tolerance through Treg/CD4+ Th2 cells potentiation." (PMID 40539049, 2025). "By integrating the results from these four algorithms, we discovered that BCL10 expression was negatively correlated with tumor-suppressing immune cells, including CD8+ T, CD4+ Th1, and NKT cells, and positively correlated with tumor-promoting immune cells, such as CD4+ Th2 and Treg cells." (PMID 40539049, 2025). "To comprehensively evaluate the correlation between BCL10 expression and the tumor immune microenvironment (TIME) and immune cell infiltration, we quantified tumor-infiltrating immune cells from RNA sequencing data using four algorithms: xCELL, QUANTISEQ, MCPcounter, and CIBERSORT." (PMID 40539049, 2025). "BCL10 may be a potential therapeutic target, and inhibition of its expression or activity may enhance tumor immunogenicity and improve the efficacy of immunotherapy." (PMID 40539049, 2025). "Therefore, even though CBM activation by BCL10 mutants promotes BTKi resistance, the enzyme nonetheless maintains key roles protecting tumor cells from apoptosis, overcome by inhibition and informing a highly promising combination with venetoclax." (PMID 39894894, 2025). "In silico analysis revealed that the upregulation of BCL10 in tumor immune microenvironment (TIME) was correlation with decreased infiltration of CD8+T cells, CD4+Th1 cells and NK T cells, and increased infiltration of Treg cells and CD4+Th2 cells in most tumors including CESC." (PMID 40539049, 2025). "BCL10 plays a dual role in different stages of tumor immunity." (PMID 40539049, 2025). "However, under chronic tumor antigen stimulation, sustained BCL10 upregulation paradoxically induces excessive activation of NF-κB, leading to T cell exhaustion." (PMID 40539049, 2025). "As a critical effector downstream of BCL10 activation, NF-κB signaling simultaneously promotes tumor cell survival and proliferation while suppressing antitumor immunity through immune cell dysregulation, thereby enabling tumor immune evasion." (PMID 40539049, 2025). "Studies have shown that high expression of BCL10 promotes liver cell proliferation and migration via activation of the AKT signaling pathway, reducing cell apoptosis, and is associated with poor prognosis of the tumor microenvironment." (PMID 39469643, 2024). "Additionally, BCL10 has been shown to contribute to the inflammatory tumor microenvironment by modulating immune responses, making it a candidate for targeted therapies." (PMID 39469643, 2024). "Furthermore, higher expression levels of ATF3, PPP1R15A, PPP2R5B, DDIT3, and BCL10 are associated with better prognosis in HER2+-BC patients, suggesting an overall tumor-suppressive role of the UPR-driven signaling cascade." (PMID 34007022, 2021). "The nuclear expression of BCL10 was detected in tumor cells of 58 patients (42.6%)." (PMID 34412631, 2021).